UFD1 (ubiquitin recognition factor in ER associated degradation 1)
Description:
Essential component of the ubiquitin-dependent proteolytic pathway which degrades ubiquitin fusion proteins. The ternary complex containing UFD1, VCP and NPLOC4 binds ubiquitinated proteins and is necessary for the export of misfolded proteins from the ER to the cytoplasm, where they are degraded by the proteasome. The NPLOC4-UFD1-VCP complex regulates spindle disassembly at the end of mitosis and is necessary for the formation of a closed nuclear envelope. It may be involved in the development of some ectoderm-derived structures (By similarity). Acts as a negative regulator of type I interferon production via the complex formed with VCP and NPLOC4, which binds to RIGI and recruits RNF125 to promote ubiquitination and degradation of RIGI.
Synonyms: UFD1L
Tractability: Small molecule: a structure with a bound ligand is known. PROTAC: ubiquitination databases record sites on it.
Gene: Protein-coding gene on chromosome 22 (19,449,911 to 19,479,215, reverse strand). Ensembl gene ENSG00000070010.
Subcellular location: Nucleus; Cytoplasm, cytosol
Subcellular location (Human Protein Atlas): Cytosol; Nucleoplasm; Nucleoli
Pathways (Reactome):
Metabolism of proteins: Neddylation; Ribosome Quality Control (RQC) complex extracts and degrades nascent peptide; Ub-specific processing proteases
Cellular responses to stimuli: KEAP1-NFE2L2 pathway
DNA Repair: Translesion Synthesis by POLH
Disease: Dengue Virus Genome Translation and Replication
Gene Ontology:
Molecular function: protein binding; cysteine-type deubiquitinase activity; polyubiquitin modification-dependent protein binding; K48-linked polyubiquitin modification-dependent protein binding
Biological process: cellular response to misfolded protein; ERAD pathway; negative regulation of RIG-I signaling pathway; negative regulation of type I interferon production; retrograde protein transport, ER to cytosol; ubiquitin-dependent protein catabolic process; proteasome-mediated ubiquitin-dependent protein catabolic process; rescue of stalled ribosome; ribosome-associated ubiquitin-dependent protein catabolic process; skeletal system development
Cellular component: nucleus; UFD1-NPL4 complex; VCP-NPL4-UFD1 AAA ATPase complex; ATPase complex; cytosol; nucleoplasm; RQC complex; cytoplasm
Genetic constraint (gnomAD): Loss-of-function variants: 13 observed, 47.22 expected, observed/expected ratio (o/e) 0.28, 90% interval 0.18 to 0.44. The upper end of that interval is the gene's LOEUF score, 0.44, which puts it in group 1 of 6, group 1 being the genes least tolerant of losing a copy. Missense variants: 215 observed, 404 expected, observed/expected ratio (o/e) 0.53, 90% interval 0.47 to 0.6. Synonymous variants: 126 observed, 145.81 expected, observed/expected ratio (o/e) 0.86, 90% interval 0.75 to 1.
Homologues: Orthologues: chimpanzee UFD1 (99% identical), dog UFD1 (99% identical), macaque UFD1 (99% identical), guinea pig UFD1 (99% identical), mouse Ufd1 (99% identical), rabbit UFD1 (98% identical), pig UFD1 (93% identical), rat Ufd1 (92% identical), tropical clawed frog ufd1 (91% identical), zebrafish ufd1l (87% identical), Drosophila melanogaster Ufd1 (59% identical), Caenorhabditis elegans ufd-1 (42% identical).
Diseases named in the same sentence as UFD1 in open-access papers:
UFD1 is named in the same sentence as 27 diseases in open-access papers, as found by Europe PMC text mining. Sharing a sentence is not in itself a finding about the gene and the disease. The quoted sentences say what the papers report.
breast carcinoma (3 papers, 2016 to 2025). "Overexpression of PCBP2 promotes the proliferation and metastasis of breast cancer cells by maintaining the mRNA stability of UFD1 and NT5E." (PMID 36052258, 2022). "PCBP2 binds to the 3’UTR of UFD1 and NT5E to upregulate the expression of these two downstream genes, which ultimately promotes the development of breast cancer." (PMID 36052258, 2022). "In addition, both UFD1 and NT5E knockdown inhibit cell proliferation, colon formation, migration and invasion in breast cancer." (PMID 36052258, 2022).
DiGeorge syndrome (3 papers, 2010 to 2020). "DGCR2, DGCR8, and UFD1 are deleted in individuals with 22q11.2 deletion syndrome (22q11DS), which occurs in individuals who have increased susceptibility for psychiatric disorders." (PMID 30923314, 2019).
Stroke (3 papers, 2007 to 2024). Sudden impairment of blood flow to a part of the brain due to occlusion or rupture of an artery to the brain. "Enzyme-linked immunosorbent assay (ELISA) was used to measure UFD1 in plasma and sera in three independent cohorts, European (Swiss and Spanish) and North-American retrospective analysis encompassing a total of 123 consecutive stroke and 90 control subjects." (PMID 19662200, 2007). "Highly significant increase of ubiquitin fusion degradation protein 1 (UFD1) was found in Swiss stroke patients with 71% sensitivity (95% CI, 52–85.8%), and 90% specificity (95% CI, 74.2–98%) (N = 31, p < 0.0001)." (PMID 19662200, 2007). "Here, we report the evaluation of UFD1 levels in three independent cohorts, demonstrating its utility as a blood biomarker of stroke." (PMID 19662200, 2007). "A significant increase of UFD1 was observed among stroke patients (p < 0.0001, Mann–Whitney test)." (PMID 19662200, 2007). "Based on the known distribution and function of UFD1, several hypotheses can be proposed regarding the mechanisms by which UFD1 may gain access to and be over-expressed in the blood of stroke patients." (PMID 19662200, 2007). "The main objective of the present study was to evaluate ubiquitin fusion degradation protein 1 (UFD1) as a new blood marker that could help in the early diagnosis of stroke patients." (PMID 19662200, 2007). "Box plots display a significant increase of UFD1 in stroke patients compared to controls." (PMID 19662200, 2007). "The exact function of UFD1 in the pathogenesis of stroke is still unknown, but recently, it has been proposed that the ubiquitin-proteasome system contributes to neurodegeneration, in particular in Parkinsons’disease and to cerebral ischemic injury." (PMID 19662200, 2007). "The present small multi-centric study tested the hypothesis that UFD1 is increased in plasma and sera samples of stroke patients." (PMID 19662200, 2007). "UFD1 emerges as a reliable plasma biomarker for the early diagnosis of stroke, and in the future, might be used in conjunction with clinical assessments, neuroimaging and other blood markers." (PMID 19662200, 2007). "Ubiquitin fusion degradation protein-1 (UFD-1), along with PARK7 and NDKA, were first detected in post-mortem CSF samples of stroke patients, and subsequently confirmed as early plasma markers of stroke." (PMID 39001884, 2024). "UFD1 was evaluated for its ability to differentiate stroke and control patients, irrespective of stroke type, lesion size or location." (PMID 19662200, 2007).
ischemic stroke (2 papers, 2007 to 2022). A stroke disorder caused by obstruction of blood flow to the brain, due to thrombotic (local blood clot formation) or embolic (due to a blood clot or other material traveling from another site) event. "Further investigations are currently underway to develop a 15-min lateral flow assay to evaluate prospectively UFD1 as a diagnostic marker of ischemic stroke and a follow-up biomarker in rtPA treated patients." (PMID 19662200, 2007). "In conclusion, UFD1 appears to be a reliable biomarker for the early diagnosis of ischemic stroke." (PMID 19662200, 2007). "As CT scan can exclude conditions such as tumor or hemorrhagic stroke, measurement of UFD1 plasma level could provide a powerful tool to rule-in ischemic stroke patients as a complement to clinical assessment and CT or MRI scan studies." (PMID 19662200, 2007). "In this context, it is hypothesized that UFD1 could be used as a follow-up marker for treated ischemic stroke patients." (PMID 19662200, 2007). "Likewise, ubiquitin fusion degradation protein 1 (UFD1) is also reported to be increased in postmortem CSF analysis and has been put forward as a serum biomarker for the early diagnosis of TIA and ischemic stroke." (PMID 35207321, 2022).
acute myocardial infarction (1 paper, 2007). Necrosis of the myocardium, as a result of interruption of the blood supply to the area. "Moreover, 12 patients with high troponin I levels (acute myocardial infarction) did not showed significant elevated concentration of UFD1 compared to controls (data not shown)." (PMID 19662200, 2007).
bladder cancer (1 paper, 2025). "For the cofactor complex UFD1/NPL4, upregulation of NPL4 is known to promote cell proliferation in bladder cancer, while suppression of NPL4 reduces cell proliferation." (PMID 41357812, 2025).
brain ischemia (1 paper, 2007). Diminished or absent blood supply to the brain caused by obstruction (thrombosis or embolism) of an artery resulting in neurologic damage. "The identification of UFD1 was based on its specific appearance in postmortem CSF presumably as a result of global brain ischemia and necrosis following death." (PMID 19662200, 2007).
dementia (1 paper, 2007). Loss of intellectual abilities interfering with an individual's social and occupational functions. "In addition, four controls with neurological disorders (dementia and meningioma) appeared negative for UFD1, suggesting specificity of the test regarding such disorders." (PMID 19662200, 2007).
Giardia infection (1 paper, 2023). "The mRNA levels of Ufd1 and Skp2 were decreased during Giardia infection, and Skp2 regulated the expressions of p21 and p27 when judged with siRNA knockdown experiments." (PMID 37006313, 2023).
lymphoblastic leukemia (1 paper, 2025). "In a study with lymphoblastic leukemia, they showed that MYC overexpression enhances the UPR system and simultaneously the ERAD system through transcriptional upregulation of UFD1." (PMID 40579643, 2025).
retinal degeneration (1 paper, 2025). Degeneration of the retina. "Depletion of seven genes (Eif2s1, Hspa5, Hspa8, Nploc4, Hyou1, Ufd1, and Vcp) showed an exacerbating effect on the Rho-Pro23His retinal degeneration compared to the Cas9+/− mice." (PMID 41282224, 2025).
Sepsis (1 paper, 2022). Sepsis is defined as life-threatening organ dysfunction caused by a dysregulated host response to infection. "CLIC1, UFD1, SEPT9, and UBE2A are new biomarkers found by us through the random forest model, and there is no research report related to sepsis so far." (PMID 35345523, 2022).
type 2 diabetes (1 paper, 2026). "Many additional gene products linked to ER quality control–dependent ubiquitin-proteasomal proteolysis also show genetic evidence of linkage to human type 2 diabetes (such as EDEM3, UFD1, NPL4, BAG1, and FAF1)." (PMID 41252202, 2026).
virus infection (1 paper, 2025). "(F) Venn diagram showing the overlap between genes upregulated upon ufd-1 RNAi and upregulated upon Orsay virus infection." (PMID 40928215, 2025).
cancer (8 papers, 2016 to 2025). A tumor composed of atypical neoplastic, often pleomorphic cells that invade other tissues. "Among the prominent genes in the ERAD pathway, Ufd1 and Cav1 genes were found to be highly expressed in the cancer group (G2) compared to the (G1) healthy control group (G2 vs. G1), while they were low expressed in all treatment groups (G3, 4 and 5)." (PMID 40579643, 2025). "They found MYC up-regulated UFD1 in T-ALL, and allelic loss of zebrafish ufd1 induced T-ALL apoptosis, impairing cancer progression." (PMID 31731471, 2019). "With about 230,000 p97 hexamers and 70,000 copies of Ufd1-Npl4 in an exemplary human cancer cell, roughly one third of the p97 hexamers could be equipped with Ufd1-Npl4 at a time." (PMID 36825201, 2023). "Based on these results, we speculate that malfunction of NPL4 or UFD1 as cofactors of VCP/P97 could be the indication of DSF treatment clinically for cancer drug development." (PMID 35290151, 2022). "In the TA of LLC‐bearing mice, a model of cancer cachexia but in C57BL/6 background, the mRNA levels of p47, Ufd2, Nploc4, and Herpud1 were all induced by about 50%, while Ufd1, Derl1, Rnf31, and Hsp90 did not change." (PMID 35611892, 2022).
infection (4 papers, 2009 to 2025). The state of being infected such as from the introduction of a foreign agent such as serum, vaccine, antigenic substance or organism. "Collectively, our findings show that inhibition of the UFD-1-NPL-4 complex triggers an aberrant immune response that is detrimental to immunocompetent worms under infection conditions but can be advantageous for immunocompromised worms." (PMID 40928215, 2025). "VCP promotion of Sif formation and intracellular wild-type Salmonella replication was impaired by knockdown of either the membrane fusion adaptor p47 or the protein degradation adaptor Ufd1, as observed following infection with the ΔsptP strain." (PMID 19286132, 2009). "Thus, our studies demonstrated that inhibition of the UFD-1-NPL-4 complex triggers an aberrant immune response that is detrimental to immunocompetent worms under infection conditions but can be advantageous for immunocompromised worms." (PMID 40928215, 2025). "Furthermore, UFD1 in grapevine was shown to be involved in responses to salt stress, light treatment, and pathogen infection during grapevine growth." (PMID 37569689, 2023).
tumor (3 papers, 2007 to 2025). "The expression of NPL4,UFD1,VCP were higher in paired tumor than adjacent normal tissues(p< 0.001).Furthermore, lower expression of NPL4 and UFD1 were significantly associated with a longer OS prognosis when VCP expression could not cause a significant OS difference." (PMID 35290151, 2022).
UFD1 also shares sentences with these, for which no sentence is quoted: schizophrenia (5 papers); psychiatric disorder (2); amyotrophic lateral sclerosis (1); bipolar disorder (1); hemorrhagic stroke (1); meningioma (1); neurological disorders (1); Opitz G/BBB syndrome (1); prostate carcinoma (1); Telangiectasia (1).